ENSG00000254732 (novel protein, C11orf31-CTNND1 readthrough)
Gene: Protein-coding gene on chromosome 11 (57,741,779 to 57,804,771, forward strand). Ensembl gene ENSG00000254732.
Genetic constraint (gnomAD): Missense variants: 19 observed, 19.04 expected, observed/expected ratio (o/e) 1, 90% interval 0.69 to 1.46. Synonymous variants: 13 observed, 8.77 expected, observed/expected ratio (o/e) 1.48, 90% interval 0.94 to 1.92.